RPL13A (ribosomal protein L13a)
Diseases named in the same sentence as RPL13A in open-access papers (continued):
Sharing a sentence is not in itself a finding about the gene and the disease.
ovarian serous tumor (1 paper, 2014). A benign, borderline, or malignant epithelial tumor of the ovary characterized by the presence of neoplastic epithelial cells that, in well differentiated tumors, resemble the epithelial cells of the fallopian tube and, in poorly differentiated tumors, show anaplastic features. "ACTB, PPIA, RPL13A, RPLP0, TBP, and B2M achieved high expression stability, which suggested that they were adequate for normalizing gene expression data among ovarian serous tumors." (PMID 24776823, 2014).
ovarian tumor (1 paper, 2024). "Additionally, the expression levels of HSPA8 and SOD1 were higher in high-grade serous ovarian cancer samples compared to non-malignant ovarian tumor tissues, while RPL13A, PSMA5, and RPSA showed the opposite trend." (PMID 38166541, 2024).
pulmonary TB (1 paper, 2025). "To identify the most stable HKGs for analyzing material from patients with pulmonary TB, we selected eight genes—ACTB, B2M, GAPDH, HPRT1, PPIA, RPL13A, YWHAZ and UBC—that are most commonly employed as reference genes in clinical studies." (PMID 41303702, 2025).
sarcoma (1 paper, 2016). A usually aggressive malignant neoplasm of the soft tissue or bone. "(3B) In CSC and native cells from sarcoma, the NormFinder software identified GAPDH, YWHAZ and 18S rRNA as the most stable genes, instead G6PD, RPL13a and B2M were the less stable." (PMID 26894994, 2016).
infection (18 papers, 2013 to 2025). The state of being infected such as from the introduction of a foreign agent such as serum, vaccine, antigenic substance or organism. "Following an infection, uL13/RPL13a exits from the 60S ribosomal subunit and forms an RNA-binding complex with the hairpin sequence within the 3′UTR of the viral matrix protein mRNA, inhibiting its translation." (PMID 39766272, 2024). "Importantly, these results were confirmed with the A/H1N1/New Caledonia/2006 influenza virus strain that was not used in the yeast two-hybrid screen, although RPL13A only scored positive 72 h post infection." (PMID 23853584, 2013).
cancer (17 papers, 2007 to 2025). A tumor composed of atypical neoplastic, often pleomorphic cells that invade other tissues. "Dysregulation including RPL13A, can lead to altered protein synthesis, often associated with cancer progression." (PMID 39891297, 2025). "On the contrary, percentages of Rpl29-expressing and Rpl13a-expressing cells were notably decreased in cancer models." (PMID 34497807, 2021). "For example, SNORD32, SNORD33A, and SNORD35A although expressed from the same host gene RPL13A are differentially modulated in different carcinomas." (PMID 30577491, 2018). "Notably, two function-unidentified ribosome protein genes, Rpl13a and Rpl29, were significantly downregulated in cancer cells." (PMID 34497807, 2021). "Thirdly, the two cancer-associated CSB mutations R1467Q and G1484R, located on the opposite side of the CSB-WHD away from its ubiquitin-binding pocket, impair RNAPII association with PPP sites of ACTB, GAPDH and RPL13A genes." (PMID 33806087, 2021). "Little could be found linking RPL13A to prognosis in cancer." (PMID 32133296, 2020). "Secondly, a cancer-associated D1425N mutation of CSB, which sensitizes cells to cisplatin, does not affect RNAPII occupancy at PPP sites of ACTB, GAPDH and RPL13A genes." (PMID 33806087, 2021).
tumor (10 papers, 2011 to 2025). "In the case of Rpl13a, there was a notable increase in the gene expression in splenic neutrophils from tumor-bearing mice." (PMID 39595137, 2024). "With this model, mutated cases with respect to the RPL13A promoter across the cohort closely followed the expected selectively neutral distribution, while TERT showed significant skew toward low-burden tumours." (PMID 36396655, 2022). "Triplicate cores from individual tumour-rich areas were obtained from FFPE samples, and extracted RNA was confirmed to be adequate for analysis, with Ct values for the house-keeping gene, RPL13a, between 22 and 28 cycles." (PMID 21952621, 2011). "Six genes, RPL13A, KLF6, LOC100129599, GBE1, PDGFA, and UHRF1 were altered in lymph node metastases of both cell lines relative the primary tumor, suggesting they may represent changes important for metastatic growth in lymph nodes." (PMID 23118918, 2012).
RPL13A also shares sentences with these, for which no sentence is quoted: acute promyelocytic leukemia (1 paper); autism (1); colon cancer (1); endothelial dysfunction (1); ependymoma (1); Herpesvirus infection (1); latent infection (1); neuroblastoma (1); ocular infections (1); Seizure (1); Sepsis (1); serous neoplasm (1); serous ovarian cancer (1); thyroid cancer (1).